NAA40 (N-alpha-acetyltransferase 40, NatD catalytic subunit)
Description:
N-alpha-acetyltransferase that specifically mediates the acetylation of the N-terminal residues of histones H4 and H2A. In contrast to other N-alpha-acetyltransferase, has a very specific selectivity for histones H4 and H2A N-terminus and specifically recognizes the 'Ser-Gly-Arg-Gly sequence'. Acts as a negative regulator of apoptosis. May play a role in hepatic lipid metabolism (By similarity).
Synonyms: NatD; hNatD; NAT11; PATT1; FLJ13848
Tractability: Small molecule: a structure with a bound ligand is known. PROTAC: ubiquitination databases record sites on it; its protein half-life has been measured; a small molecule that binds it is known.
Target class: Enzyme; Transferase
Gene: Protein-coding gene on chromosome 11 (63,938,669 to 63,957,319, forward strand). Ensembl gene ENSG00000110583.
Subcellular location: Cytoplasm; Nucleus
Subcellular location (Human Protein Atlas): Nucleoplasm; Centriolar satellite; Cytosol
Gene Ontology:
Molecular function: histone H2A acetyltransferase activity; histone H4 acetyltransferase activity; protein binding; protein N-terminal-serine acetyltransferase activity; acyltransferase activity, transferring groups other than amino-acyl groups
Biological process: chromatin remodeling
Cellular component: cytoplasm; cytosol; nucleoplasm; nucleus
Genetic constraint (gnomAD): Loss-of-function variants: 26 observed, 37.79 expected, observed/expected ratio (o/e) 0.69, 90% interval 0.5 to 0.95. The upper end of that interval is the gene's LOEUF score, 0.95, which puts it in group 4 of 6, group 1 being the genes least tolerant of losing a copy. Missense variants: 237 observed, 320.53 expected, observed/expected ratio (o/e) 0.74, 90% interval 0.66 to 0.82. Synonymous variants: 129 observed, 113.4 expected, observed/expected ratio (o/e) 1.14, 90% interval 0.99 to 1.32.
Homologues: Orthologues: chimpanzee NAA40 (100% identical), mouse Naa40 (99% identical), rabbit NAA40 (98% identical), pig NAA40 (98% identical), rat Naa40 (98% identical), guinea pig NAA40 (97% identical), dog NAA40 (96% identical), zebrafish naa40 (84% identical), tropical clawed frog naa40 (81% identical), macaque NAA40 (80% identical), zebrafish NAA40 (45% identical), Drosophila melanogaster Naa40 (29% identical), and 1 more.
Diseases named in the same sentence as NAA40 in open-access papers:
NAA40 is named in the same sentence as 12 diseases in open-access papers, as found by Europe PMC text mining. Sharing a sentence is not in itself a finding about the gene and the disease. The quoted sentences say what the papers report.
colorectal cancer (9 papers, 2016 to 2025). A primary or metastatic malignant neoplasm that affects the colon or rectum. "Taken together, our data show that loss of Naa40 induces apoptosis in HCT116 colorectal cancer cells." (PMID 26666750, 2016). "Overall, these data associate Naa40 to colorectal cancer development and highlight the potential exploitation of Naa40 as a therapeutic target." (PMID 26666750, 2016). "Collectively, these findings reveal NAA40 as novel regulator of cancer cell metabolism and provide new insight for predicting or overcoming therapy resistance in colorectal cancer." (PMID 34785778, 2022). "Considering that NAA40 was recently reported to be significantly elevated in colorectal cancer (CRC) tissues and stimulated tumour cell growth in vitro and in vivo, we sought to investigate its molecular role in CRC." (PMID 34785778, 2022). "Collectively, these data suggest that in colorectal cancer cells NAA40-mediated regulation of one-carbon metabolic gene expression controls the global levels of different histone methylation marks." (PMID 34785778, 2022). "Altogether, these findings reveal an anti-apoptotic role for Naa40 and exhibit its potential as a therapeutic target in colorectal cancers." (PMID 26666750, 2016). "The present data reveal an anti-apoptotic role for Naa40 in colorectal cancer cells, highlighting the importance of this enzyme in human cells." (PMID 26666750, 2016). "It has been previously reported that upregulation of NAA40 occurs from early stages of colorectal cancer, but not of lung cancer where it is mainly associated with more advanced tumour stages." (PMID 34150665, 2021). "NAA40 has recently been reported to have oncogenic functions in lung and colorectal cancers." (PMID 32942614, 2020). "Conversely, we have previously unveiled a pro-survival role for NAA40 in colorectal cancer (CRC) cells suggesting that it may stimulate cancer cell growth." (PMID 30858358, 2019). "To investigate whether human Naa40 has the same effect on ribosomal RNA (rRNA) expression, we depleted Naa40 in HCT116 colorectal cancer cells using two different siRNAs." (PMID 26666750, 2016). "Hence, our results strongly favor the idea that NAA40 is a critical mediator at the interface between epigenetics and metabolism by linking one-carbon cycle to drug response and signify its potential as a novel predictive factor and therapeutic target in colorectal cancer." (PMID 34785778, 2022). "Additionally, epigenetic alterations, such as N-alpha-acetyltransferase 40 (NAA40)-induced acetylation, have been reported to contribute to PRMT5 overexpression in colorectal cancer." (PMID 38666828, 2024). "PRMT5 could be repressed by N-alpha-acetyltransferase 40 (NAA40), which results in downregulating key oncogene expressions, upregulating tumor suppressor genes levels, and finally leading to inhibiting colorectal cancer cell growth." (PMID 34124017, 2021). "Altogether, these results suggest that Naa40 depletion induces apoptosis in colorectal cancer cells, but does not affect the viability of non-malignant cells." (PMID 26666750, 2016). "In accordance with the existing literature, NAA40 and TYMS were found to be elevated in colorectal cancer patients as opposed to normal colon tissues." (PMID 34785778, 2022). "To determine whether induction of apoptosis upon Naa40-knockdown is specific to HCT116 cells, we also depleted this enzyme in another colorectal cancer cell line (HT-29) and non-cancerous mouse embryonic (STO) fibroblasts." (PMID 26666750, 2016).
hepatocellular carcinoma (5 papers, 2013 to 2020). A malignant tumor that arises from hepatocytes. "Naa40 was previously linked to apoptosis but, in contrast to our findings, it was shown that siRNA mediated knockdown of Naa40 protects hepatoma cells from drug-induced apoptosis." (PMID 26666750, 2016). "An additional article reported that NAA40 is downregulated in hepatocellular carcinoma tissues compared to its highly expressed levels in normal liver specimens supporting a potential context-specific tumour suppressive property of NAA40." (PMID 32680559, 2020). "In a recent study, Naa40 was shown to be downregulated in hepatocellular carcinoma whereas its overexpression enhanced drug-induced apoptosis that was dependent on its acetyltransferase activity." (PMID 26666750, 2016). "Moreover, NAA40 was shown to be downregulated in hepatocellular carcinoma tissues and ectopic NAA40 expression sensitizes hepatoma cancer cell lines to drug-induced apoptosis." (PMID 30858358, 2019). "Determining whether Naa40 utilizes a similar mechanism to control gene activation in mammalian cells is intriguing, considering that this enzyme has a pro-apoptotic function and was found significantly downregulated in hepatocellular carcinomas." (PMID 24068969, 2013).
lung carcinoma (3 papers, 2019 to 2021). "Notably, a decrease in H4R3me2s levels upon loss of human NAA40 and N-acH4 has also been detected in lung cancer cells." (PMID 30858358, 2019). "In lung cancer cells knockdown of NAA40 was shown to reduce invasion and metastasis in vitro and in vivo." (PMID 32680559, 2020). "In particular, a recent study has indicated that NAA40 is a critical regulator of cell invasion during lung cancer metastasis." (PMID 30858358, 2019). "In addition NAA40 has been reported to be required for the survival and invasion abilities of colorectal and lung cancer cells, respectively, highlighting its potential as a therapeutic target." (PMID 32680559, 2020).
colon cancer (2 papers, 2016 to 2019). "Taken together, our results establish the oncogenic function of the epigenetic enzyme NAA40 in colon cancer and support its potential as a therapeutic target." (PMID 30858358, 2019). "To determine the apoptotic pathway that is induced by depletion of Naa40 in colon cancer cells, we first investigated its effect on caspase activation." (PMID 26666750, 2016). "Taken together, these results demonstrate that activation of caspase-9 and thus, the mitochondrial pathway are essential for the induction of apoptosis in colon cancer cells depleted of Naa40." (PMID 26666750, 2016). "Specifically, Naa40 knockdown in colon cancer cells activates the mitochondrial caspase-9-mediated apoptotic cascade." (PMID 26666750, 2016). "Initially, we show that depletion of Naa40 in colon cancer cells results in reduced ribosomal RNA expression, which is consistent with the recently described function of yeast Naa40." (PMID 26666750, 2016). "Collectively, our results verify the conclusion that Naa40 depletion triggers apoptosis in colon cancer cells and reveal the involvement of caspases within this process." (PMID 26666750, 2016). "However, prior to the usage of NAA40-specific pharmacological inhibitors for colon cancer treatment, further studies are required to determine the effects of NAA40 depletion in normal colonic cells." (PMID 30858358, 2019). "Thus, overall these findings suggest that NAA40 facilitates survival of colon cancer cells partly through upregulation of PRMT5 expression." (PMID 30858358, 2019). "We have previously shown that NAA40 activity controls the survival of colon cancer cells." (PMID 30858358, 2019). "Our results imply that ribosomal DNA silencing and consequently impaired ribosome biogenesis as a result of Naa40 loss, could be the triggers for inducing apoptosis in HCT116 and HT-29 colon cancer cells." (PMID 26666750, 2016). "We show that depletion of Naa40 in colon cancer cells triggers a strong apoptotic response." (PMID 26666750, 2016). "To further evaluate the role of NAA40 in the context of CRC cell growth, we constructed an inducible system to downregulate NAA40 upon doxycycline (dox) treatment of HCT116, HT-29, SW480, and SW620 colon cancer cell lines." (PMID 30858358, 2019). "To explore the clinical relevance of NAA40 expression in patients with CRC, we initially examined NAA40 protein levels on tissue microarrays harboring colon cancer tissues and adjacent normal specimens." (PMID 30858358, 2019). "Knockdown of Naa40 in HCT116 and HT-29 colon cancer cells affects their survival by caspase-9 activation." (PMID 26666750, 2016). "We then show that Naa40 is required for the survival of HCT116 and HT-29 colon cancer cells since its depletion induces apoptotic cell-death." (PMID 26666750, 2016). "Taken together, our data show that lack of NAA40 suppresses in vitro growth of colon cancer cell lines and enhances the sensitivity of CRC cells to 5-FU." (PMID 30858358, 2019). "Firstly, Naa40 knockdown in colon cancer cells induces a strong apoptotic effect but depletion in noncancerous mouse embryonic fibroblasts does not affect cell viability." (PMID 26666750, 2016).
Hepatic steatosis (2 papers, 2020 to 2022). Steatosis is a term used to denote lipid accumulation within hepatocytes. "In addition, the implication of NAA40 in hepatic steatosis and glucose sensing led us to hypothesise that this enzyme may impinge on cellular metabolism in the liver." (PMID 35057804, 2022).
liver cancer (2 papers, 2020 to 2021). An epithelial or non-epithelial malignant neoplasm that arises from the liver. "Next, we examined the association of NAA40 expression in LIHC with various known liver cancer etiological factors." (PMID 34150665, 2021). "Hence, the upregulation NAA40 is a common event in liver cancer and is associated with worse patient survival." (PMID 32942614, 2020). "We also noted that expression of NAA40 in liver cancer cell lines was comparable to cell lines derived from other tumour types, unlike in tissues derived from normal organs where its expression differs significantly." (PMID 34150665, 2021). "It was apparent that the increase in NAA40 transcript levels is an early and persistent event during liver cancer progression." (PMID 34150665, 2021). "Next, to gain insight about the biological processes with which NAA40 is associated in liver cancer, we used the SEEK tool to examine genes and pathways correlating with NAA40 expression across 107 liver cancer datasets." (PMID 32942614, 2020). "Surprisingly, despite the evident upregulation of NAA40 in liver cancer, it remains the tumour tissue with the lowest NAA40 expression in the TCGA pan-cancer study (left)." (PMID 32942614, 2020).
colon adenocarcinoma (1 paper, 2019). "Immunofluorescence analysis showed that NAA40 is increased in colon adenocarcinomas compared to benign lesions and normal colon specimens." (PMID 30858358, 2019).
colorectal tumours (1 paper, 2022). "Notably, NAA40-mediated activation of the 1C-metabolic gene TYMS confers 5-FU resistance to CRC cells and in human colorectal tumours NAA40 expression positively correlates with TYMS levels and worse response of patients to 5-FU-based chemotherapy." (PMID 34785778, 2022).
cancer (11 papers, 2016 to 2025). A tumor composed of atypical neoplastic, often pleomorphic cells that invade other tissues. "Multiple independent datasets thus concur on a transcriptional co-expression association of the two genes, H2A.X and NAA40 in cancers." (PMID 40665417, 2025). "Gene Ontology (GO) analysis of the differentially expressed genes illustrated that loss of NAA40 alters sets of genes involved in cancer-related processes in support of our previous finding." (PMID 34785778, 2022). "In conclusion, our analyses of genomic alterations of NATs in cancers found these to be relatively low frequency events, with some notable exceptions, such as NAA40 amplification in UCS, and NAA15 truncating mutations in UCEC." (PMID 32942614, 2020). "Over-activation of E2F pathway is also known to be common in human cancers, and could potentially underlie the upregulation of the NAA40 transcript in several tumour types." (PMID 38864963, 2025). "Fourth, consistent with the reported upregulation of NAA40 in cancer, we found that Nt-acH2A.XK5ac levels were significantly higher in cancerous cell lines than in non-cancerous cells." (PMID 40665417, 2025). "Based on these findings we and others have argued that NAA40 is a promising candidate target for cancer therapy." (PMID 40665417, 2025). "A recent multi-omic analysis revealed that NAA40 is upregulated in a diverse range of tumours and correlates with poor overall survival of cancer patients." (PMID 34785778, 2022). "In contrast, we do not detect major changes in metabolite levels of other central metabolic pathways, such as glycolysis in these cancer cells, indicating that the effects of NAA40 knockdown are specific towards 1C-metabolism." (PMID 34785778, 2022). "Overall, these findings define a novel regulatory link between epigenetics and cellular metabolism mediated by NAA40, which is harnessed by cancer cells to evade chemotherapy." (PMID 34785778, 2022). "Viewing the aberrant and highly variable NAA40 expression observed in a variety of cancers, expression profiling at the level of proteoforms thus appears a prerequisite to further unravel the (distinct) roles of Naa40p proteoforms in disease." (PMID 33916271, 2021). "Evidence for the involvement of NAA40 in cancer has also been presented in recently published studies." (PMID 32680559, 2020). "The potential of NAA40 to serve as a target in anticancer therapy is also reinforced by the data here which show its ability to sensitize CRC cancer cells toward conventional chemotherapeutic drugs such as 5-FU." (PMID 30858358, 2019). "The results also indicate that in CRC cells NAA40 regulates H4R3me2s levels through transcriptional control of PRMT5, which subsequently modulates the expression of its cancer-associated target genes." (PMID 30858358, 2019). "Altogether, these results suggest that NAA40 promotes PRMT5 transcriptional activation, which in turn influences the expression of vital cancer-associated genes in CRC cells." (PMID 30858358, 2019). "In summary, our findings reveal a conserved role of hNaa40 in the control of rRNA expression and, mainly, link Naa40 to cancer cell apoptosis." (PMID 26666750, 2016). "According to the Human Protein Atlas project, Naa40 protein levels vary in different cancer types, with the highest expression observed in colorectal, ovarian and prostate cancers and the lowest in lymphomas, glioma, renal and liver cancers." (PMID 26666750, 2016).